HIF1A (hypoxia inducible factor 1 subunit alpha)
Diseases named in the same sentence as HIF1A in open-access papers (continued):
Sharing a sentence is not in itself a finding about the gene and the disease.
iron deficiency (continued). "HIF1α was identified as an intermediate in FGF23 mRNA upregulation: iron deficiency and hypoxia only stabilized pre-existing HIF1α, where inflammation also led to increased cellular expression of HIF1α in bone cell lines." (PMID 30971944, 2019). "Mechanistically, inflammation and iron deficiency increase the activity of the hypoxia-inducible factor 1-alpha (HIF-1α) signaling, thereby augmenting Fgf23 transcription." (PMID 30909513, 2019). "To further probe the functional consequences of iron-deficiency in the Gaa-KO brain, we also tested if HIF-1α was accumulating, by western blot, and found an increase in its levels in Gaa-KO cortex both at 6- and 12 months." (PMID 31793879, 2019). "Iron deficiency induced by iron chelation stabilized pre-existing HIF1α and increased FGF23 transcription." (PMID 30971944, 2019). "HIF1α stabilization under conditions of iron deficiency has been associated with upregulation of furin in liver cells." (PMID 30971944, 2019). "The observation that cFGF-23 decreased significantly after i.v. iron treatment suggests that cFGF-23 reflects the transcriptional activity of the FGF-23 promoter, which is induced by iron deficiency via hypoxia inducible factor 1 alpha (HIF-1α)." (PMID 27907058, 2016). "The levels of HIF1α in wild-type mice with iron deficiency were also shown to increase, indicating the importance of HIF1α in hypoxia-mediated repression of Hamp." (PMID 26182354, 2015). "In view of the importance of iron deficiency in hypoxia inducible factor-1alpha (HIF-1α) stabilization and the role of HIF-1α in Notch signaling, iron deficiency-mediated HIF-1α is a relevant pathway to be investigated in the future." (PMID 23800380, 2013). "The generation of sHJV appears to be increased by iron deficiency and hypoxia in association with the stabilization of HIF1α." (PMID 20467559, 2010). "In hypoxia or iron deficiency, HIF1α accumulates, translocates to the nucleus, and associates with HIF1β, a constitutively expressed HIF subunit." (PMID 20467559, 2010). "To further associate iron deficiency with HIF-1α, VEGF, and angiogenesis, we showed that iron supplementation caused a destabilization of HIF-1α, a result which supports the idea that iron deficiency contributes to HIF-1α induction and stabilization." (PMID 20723262, 2010). "Moreover, the iron deficiency‐induced increase in HIF‐1α downregulates the expression of PPAR‐α and CPT1A, key genes involved in fatty acid oxidation, thereby reducing lipid catabolism and promoting lipid accumulation." (PMID 41566725, 2026). "Additionally, iron deficiency upregulates HIF‐1α, which modulates glucose transporters (GLUT1 and GLUT3), thereby altering cellular glucose uptake." (PMID 41566725, 2026). "Given the discrepancy between how HIF1α responded in CD8+ T cells under iron chelation and iron deficiency, we were interested to understand whether the difference in cellular response extended beyond HIF1α." (PMID 40541943, 2025). "Thus, iron deficiency has been reported to have important effects on HIF-1α stabilization, VEGF formation, angiogenesis and tumor progression in breast cancer, in both in vitro and in vivo studies." (PMID 33777027, 2021). "HIF1α is stabilized in case of hypoxia or iron deficiency and activates downstream pathways." (PMID 33716961, 2021). "In cell iron deficiency, Cp expression is, in part, regulated by HIF-1α." (PMID 34310628, 2021). "Furthermore, the Gaa-KO fibroblasts show a decrease in Fe2+, in agreement with the iron deficiency response and the accumulation of HIF-1α." (PMID 31793879, 2019). "Therefore, inhibition of lysosomal acidification using a genetic approach also results in functional iron deficiency and HIF-1α activation." (PMID 31793879, 2019).
iron deficiency (continued). "Using intestinal epithelial cell-specific knockouts of Hif1α and Hif2α it was demonstrated that Hif2α is required for iron absorption, as mice lacking Hif2α in the intestinal epithelium developed a marked iron deficiency, characterized by low liver and serum iron levels." (PMID 26182354, 2015). "Iron deficiency has been described to stimulate HIF1α leading to increased FGF-23 transcription." (PMID 23555610, 2013). "During hypoxia or iron deficiency, PHDs are inactivated, allowing HIF-1α /HIF-2β to accumulate." (PMID 22194696, 2011). "We have hypothesized that, in young premenopausal women, an iron deficiency caused by menstruation stabilizes HIF-1α, which increases the formation of VEGF." (PMID 20723262, 2010). "In the present study, we hypothesized that iron deficiency, a common ailment in young women, contributes to the poor outcome by promoting the hypoxia inducible factor-1α (HIF-1α and vascular endothelial growth factor (VEGF) formation." (PMID 20723262, 2010). "In fact, iron deficiency increases HIF-1α levels in mice liver." (PMID 21415988, 2009). "Notably, our data revealed that 12-week-old of hIAPP-Tg mice showed iron deficiency in islets, which might trigger the activation of the HIF1α signaling pathway and lead to increased glycolysis." (PMID 36922503, 2023). "In addition, iron-deficiency also induced increments of Hypoxia Inducible Factor 1α (HIF1α), and HIF1α itself could also boost FGF23 expression." (PMID 35629904, 2022). "We hypothesized that iron deficiency affects mucosal HIF1α activity in IBD." (PMID 35755436, 2022). "Future research should delve deeper into key biomarkers, including HIF-1α, VEGF, EPO, iron deficiency markers, and hepcidin levels." (PMID 39940380, 2025). "There are many reports in the literature confirming that iron deficiency, by limiting the activity of the PHD enzyme, stabilizes HIF-1α by increasing its level in the cell." (PMID 39456823, 2024). "Under conditions of hypoxia or cellular iron deficiency, the activity of PHD is inhibited, leading to increased stability of HIF-1α." (PMID 38493104, 2024). "Treatment with PX478, an inhibitor of HIF1α, and Mithramycin A, an inhibitor of Sp1, resulted in a reversal of the upregulation of SPNS2 mRNA and protein expression caused by iron deficiency, with Mithramycin A exhibiting a more pronounced effect." (PMID 39228402, 2024). "Dox is a strong iron chelator, therefore, the iron deficiency caused by is deficiency inhibits HIF-PH activity, causing normoxic HIF1A accumulation." (PMID 36602546, 2023). "Iron deficiency also upregulates FURIN transcription through stabilization of HIF-1α, whereas iron overload inhibits furin expression in a non-HIF-1α-dependent manner." (PMID 35996194, 2022). "Iron deficiency and inflammation are both able to alter FGF23 transcription via hypoxia inducible factor 1 α (HIF1α)." (PMID 33716961, 2021). "These discoveries suggest that absolute iron deficiency, characterized by a depletion of both iron stores and circulating iron, promotes FGF23 transcription through Hif1α." (PMID 32982979, 2020). "Both iron deficiency and inflammation increase FGF23 transcription by activating among other signaling pathways, Hif1α, and associated MAPK signaling, in osteocytes." (PMID 32982979, 2020). "Inhibition of iFGF23 signaling with rh-cFGF23 in CKD mice resulted in decreased erythroid cell apoptosis, upregulation of renal and BM HIF1α and subsequent EPO mRNA expression, elevated serum EPO levels and amelioration of iron deficiency." (PMID 30971944, 2019). "The findings indicated that iron deficiency specifically upregulated the transcriptional activity of HIF1α and Sp1 on SPNS2, with Sp1 demonstrating a more pronounced increase in transcriptional activity compared to HIF1α." (PMID 39228402, 2024). "Moreover, HIF1α is believed to be involved in altered FGF23 cleavage seen in inflammation and iron deficiency." (PMID 33716961, 2021).
iron deficiency (continued). "Finally, recent studies have highlighted a novel mechanism linking v-ATPase inhibition, hypoxia-inducible factor 1 alpha (HIF-1α) signaling and iron deficiency." (PMID 34143769, 2021). "PHDs also use iron as a cofactor for enzymatic activity, thus HIF-1α can be induced by iron deficiency independent of oxygen status." (PMID 33553263, 2020). "However, the ATP6AP1KO cells showed no iron-deficiency-induced Hif1α activation, nor were they more susceptible to deferoxamine-induced iron depletion." (PMID 41339359, 2025). "Summarizing, inflammation does augment both FGF23 expression and its cleavage, by increased HIF1α expression and stabilization and increased furin activity, but also via hepcidin-induced functional iron deficiency and subsequent non-hypoxic HIF1α stabilization." (PMID 30971944, 2019). "Using a hepatocyte-specific Hif2α knockout mouse, it was shown that in conditions of iron-deficiency HIF2α is not required for the repression of hepcidin, however mice with a constitutively active HIF2α (Vhlh/Hif1α double knockout mice) had lower hepcidin levels in their livers." (PMID 26182354, 2015). "Peyssonnaux and colleagues demonstrated that the expected hepcidin downregulation in response to dietary iron deficiency was partially blunted in hepatocyte-specific HIF-1α knockout mice as compared to wild-type animals, suggesting that HIF-1α might be a negative regulator of hepcidin signaling." (PMID 21912548, 2011). "Our results, along with the established findings of HIF-mediated increase in TfR1 expression, indicate that IDA induces hypoxia and stabilizes HIF-1α and, in turn, hypoxia increases cellular iron uptake to combat iron deficiency through negative feedback of the hypoxic conditions." (PMID 20723262, 2010). "Additionally, the elevation of HIF-1α enhanced hepcidin/ferroportin 1 (FPN1)-mediated iron efflux and resulted in cellular iron deficiency, which led to the functional accumulation of the dopamine transporter (DAT) in plasma membranes due to iron deficiency-impaired ubiquitin degradation." (PMID 37718358, 2023).
thyroid cancer (58 papers, 2013 to 2025). "In thyroid cancer, studies have suggested that hypoxia-inducible factors, particularly HIF-1α, are associated with tumor aggressiveness and metastasis." (PMID 37629778, 2023). "The xpression of HIF-1α in human thyroid cancer tissues is associated with tumor aggressiveness, and dedifferentiated anaplastic thyroid cancer has shown particularly high expression of HIF-1α." (PMID 32847004, 2020). "In thyroid cancer, HIF-1α, BRAF mutation, and TSHR signaling are considered key regulators." (PMID 41301693, 2025). "HIF1A causes alterations in the immunological microenvironment of thyroid cancer, which may be associated with ferroptosis of thyroid cells produced by an increase in ROS." (PMID 36937508, 2023). "Estrogen in the thyroid gland can upregulate VEGF levels, and it has been shown that increased intracellular ROS in thyroid cancer causes HIF-1α overexpression, and sustained and stable release of VEGF, but antioxidants N-acetylcysteine can eliminate these effects." (PMID 33996538, 2021). "The tight association of HIF-1α with metabolic pathways may be a pleasant target for better therapy of thyroid cancers." (PMID 32493394, 2020). "In addition, in our previous study that evaluated factors associated with 18F-fluorodeoxyglucose avidity in primary thyroid cancer, HIF-1α was the candidate protein identified for its involvement in altered metabolism and acquisition of aggressiveness." (PMID 32847004, 2020). "Correlation analysis revealed a strong positive association between HIF1A expression and TPM4 levels in PTC cells, further supporting the interconnected nature of hypoxia response and TPM4-mediated EMT processe in thyroid cancer progression." (PMID 40740237, 2025). "Research has demonstrated that the target genes HIF-1α regulates in thyroid cancer are crucial for tumor cell metabolism, angiogenesis, cell division, metastasis, and immune evasion." (PMID 40917751, 2025). "We discuss how mtDNA alterations disrupt oxidative phosphorylation (OXPHOS), trigger adaptive metabolic rewiring, and interact with key oncogenic pathways, such as HIF-1α, BRAFV600E mutations, and TSHR signaling in thyroid cancer." (PMID 41301693, 2025). "In summary, HIF-1α, BRAF mutations, and TSHR signaling synergistically contribute to metabolic plasticity in thyroid cancer, representing key mechanisms underlying metabolic reprogramming and drug resistance." (PMID 41301693, 2025). "The expression of the LDH gene can be regulated by specific transcription factors, including c-Myc and hypoxia-inducible factor-1α, thyroid cancer cells usually exhibit elevated c-Myc and HIF-1α activity, which promotes LDH expression." (PMID 40917751, 2025). "HIF-1α further regulates the stemness of thyroid cancer and promotes cancer progression via the HIF-1α/microRNA-146a/DKK1 axis." (PMID 40164592, 2025). "Compared with adjacent normal thyroid tissue, TC is mainly characterized by areas of Hypoxia inducible factor-1 (HIF-1α)-mediated hypoxia and has a wide range of implications for malignant progression and poor outlook of thyroid cancer." (PMID 39776907, 2024). "Artemisinin, an antimalarial drug, suppresses the pro-oncogenic effect of XIST and inhibits aerobic glycolysis, proliferation, and metastatic potential of thyroid cancer cells through the degradation of hypoxia-inducible factor 1α (HIF-1α)." (PMID 39458944, 2024). "We next tested the effect of ectopic expression or deletion of TET1 on HIF1α expression in thyroid cancer cells." (PMID 37020036, 2023). "This forms a feedback loop in which TET1 promotes thyroid cancer progression via the CK2/AKT/GSK3β/HIF1α signaling pathway." (PMID 37020036, 2023). "In summary, this study demonstrates that TET1 plays distinct roles under in vitro and in vivo conditions in cancer, such as thyroid cancer, which is due to the different oxygen environments; hypoxia switches on its oncogenic functions through HIF1α." (PMID 37020036, 2023).
thyroid cancer (continued). "Further studies demonstrated that Slit2 regulated Hif-1α expression to affect thyroid cancer cells; however, inhibition of miR-200b-3p targeting and downregulation of Slit2 improved hypoxia-ischemic brain damage." (PMID 37097589, 2023). "The effect of high HIF1A expression in OSAS on thyroid cancer survival discovered that HIF1A expression in thyroid tissue was also increased, and patients with high HIF1A expression had a lower survival time." (PMID 36937508, 2023). "In this study, we will verify the mechanism that XIST regulates glycolysis of thyroid cancer cells through HIF-1a, and explore XIST as a biomarker of thyroid cancer progression and corresponding intervention measures." (PMID 37036874, 2023). "An article reported that the BRAFV600E mutation, which occurs in ~45% of patients with PTC, affects HIF1-α expression in thyroid cancers by regulating hypoxia and the BRAFV600E-mediated signaling pathway." (PMID 36428988, 2022). "NOX4 or p22phox downregulation decreases mitochondrial ROS in hypoxic thyroid cancer cells, impairs HIF1α stabilization, HIF1α-induced glycolysis increment, and cell proliferation." (PMID 35682803, 2022). "Collectively, these reports suggest that HIF1-α is closely related to the pathophysiology of thyroid cancer, specifically in terms of tumor aggressiveness, progression, and metastasis with characteristics of dedifferentiation." (PMID 36428988, 2022). "All these results proved that KDM1A can regulate the transcription of DKK1 via HIF-1α/miR-146a axis; and then activate the Wnt pathway to promote the stemness and chemotherapeutic resistance of thyroid cancer." (PMID 35198054, 2022). "The four thyroid cancer cell lines and one thyroid follicular epithelial cell line demonstrated accelerated HIF1-α expression in the 3D spheroid culture, but this was low/undetectable in the 2D monolayer culture." (PMID 36428988, 2022). "Hyperactive PI3K signaling leads to stabilization of HIF-1α not only in normoxia but also in many cancers, including thyroid cancer and is predominantly involved in the metastasis of PTC and FTC." (PMID 36699028, 2022). "NOX can regulate glycolysis through the mROS-HIF1α pathway and maintains HIF1α stability, thereby mediating proliferation in thyroid carcinomas." (PMID 35571253, 2022). "Thereafter, Kim and colleagues showed that pharmacological targeting of HIF-1α can be a promising approach for thyroid cancers treatment." (PMID 34539584, 2021). "Our study demonstrated that ENO1 was an oncogene in thyroid carcinoma that acted downstream of mTOR/HIF1α and accelerated thyroid carcinoma progression via regulating CST1." (PMID 33968941, 2021). "In thyroid cells, HIF-1α is also known to be implicated in VEGF-A upregulation and angiogenesis with an increase of VEGF-A being a hallmark of thyroid carcinomas." (PMID 33916948, 2021). "Other studies have also identified associations between HIF-1α and high TNM stage or lymph node metastases in immunohistochemical studies of human thyroid cancer tissues." (PMID 32847004, 2020). "In various cancers, including thyroid cancer, overexpression of HIF-1α is related to poor prognosis or treatment response." (PMID 32847004, 2020). "In this study, we evaluated the status of HIF-1α expression in several thyroid cancer cell lines and the effects of HIF-1α inhibitor (IDF-11774) treatment on thyroid cancer progression." (PMID 32847004, 2020). "We evaluated the utility of the HIF-1α inhibitor IDF-11774 in vitro utilizing two thyroid cancer cell lines, K1 and BCPAP." (PMID 32847004, 2020). "The inhibition of HIF-1α expression reduces the induction of CAIX levels under hypoxic conditions in thyroid carcinoma." (PMID 32823915, 2020). "Results showed that in both thyroid cancer cell lines vitamin C induced a dose-dependent decrease of HIF-1α protein level." (PMID 29084538, 2017).